CD69 (CD69 molecule)
Diseases named in the same sentence as CD69 in open-access papers (continued):
Sharing a sentence is not in itself a finding about the gene and the disease.
leukemia (continued). "Mock T cells did not upregulate CD69 or CD25 after co-incubation with KOPN8 leukemia cells." (PMID 31195686, 2019). "Despite this, we could not observe any increase in the expression of the surface marker CD69 in thymic, splenic, or bone–marrow derived leukemia/lymphoma cells by flow cytometry (data not shown)." (PMID 20011522, 2009). "Moreover, CSPG4-CAR T cells exhibited a significantly higher CD69 and CD25 expression upon co-culture with KOPN8 leukemia cells as compared to co-incubation with CSPG4-negative T2.A1 cells, further corroborating antigen-specific activity of CSPG4-CAR T cells in response to KOPN8 leukemia cells." (PMID 31195686, 2019). "In addition, significant increase in the numbers of total or activated (CD69+) CD8 T cells were observed in spleen, but not in BM, of the mice transplanted with MLL/AF9 leukemia cells irrespective of OVA expression." (PMID 26658107, 2015).
Arthritis (18 papers, 2005 to 2024). Inflammation of a joint. "CD69 deficient mice display more severe clinical pictures in the collagen induced arthritis and autoimmune myocarditis murine models and show an enhanced differentiation toward Th17 cells." (PMID 37809329, 2023). "A reduced level of TGF-β1 plays a major role in exacerbating the severity of arthritis in a CD69-deficient mouse model." (PMID 23658623, 2013). "A similar correlation between the number of iNKT cells and the clinical severity of arthritis, as well as an increased expression of CD69 by iNKT cells, was observed in joint-draining lymph nodes." (PMID 29980684, 2018). "Blocking CD69 impairs oral tolerance, exacerbates arthritis as well as other autoimmune disorders by blocking the differentiation of Th17 lymphocytes." (PMID 24341794, 2013). "With respect to autoimmunity, CD69-/- mice showed a higher incidence and severity of collagen-induced arthritis, which again were correlated with reduced levels of TGFβ." (PMID 19543397, 2009). "Furthermore, expression of the activation marker CD69 was significantly increased on ankle iNKT cells during arthritis development." (PMID 29980684, 2018). "CD69 deficiency leads to diminished levels of TGF-β that contribute to an enhanced immune response, resulting in increased inflammation in a collagen-induced arthritis model." (PMID 25948100, 2015). "Because CD69 potentially plays a role in the pathogenesis of arthritis, our findings suggest that neutrophils are among the targets of anti-TNF-α activity in RA and may provide an insight into a new and interesting mechanism of action of anti-TNF-α mAbs in the control of inflammatory arthritis." (PMID 15743471, 2005). "Furthermore, Murata and coworkers recently reported that CD69-null mice were protected from collagen-induced arthritis, and that transfer of neutrophils from wild-type mice could restore arthritis in these animals." (PMID 15743471, 2005). "Mice lacking the CD69 transmembrane receptor develop aggravated forms of autoimmune pathologies including arthritis, contact dermatitis, allergic asthma, and autoimmune myocarditis." (PMID 27256343, 2016).
Autoimmunity (17 papers, 2009 to 2026). The occurrence of an immune reaction against the organism's own cells or tissues. "CD69 encodes for CD69, an activated marker for B and T cells that is pivotal in autoimmunity." (PMID 36609529, 2023). "Females that had another associated autoimmune condition had an elevated CD69 expression and a decreased BCL2 expression compared with females without an autoimmune condition indicating an activated and exhausted phenotype in chronically affected study participants." (PMID 36741413, 2022). "These antibodies showed biased immunoglobulin V-domain usage, linked to a CD69/CD83 plasma cell state associated with disease severity and degree of autoimmunity." (PMID 41646792, 2026). "These cells exert their regulatory functions via a number of unique surface regulatory molecules, including LAG3 and CD69, acting separately or synergistically to diminish inflammation, including Th17-driven autoimmunity." (PMID 25880134, 2015). "CD69 has been identified as a B cell marker associated with MS whereas CD80 and CD86 are costimulatory molecules that are involved in immune regulation and B cells expressing CD80/CD86 have been shown to drive pathogenesis in autoimmunity." (PMID 36389698, 2022). "CD69+ cells have been proposed to downregulate autoimmunity by producing TGF-β." (PMID 27999289, 2016). "Within the kidneys, we were able to identify a specialized subset of autoreactive CD69+CD103+ T cells that bears canonical hallmarks of TRM cells and likely plays a pivotal role in sustaining long-lasting local autoimmunity." (PMID 38961265, 2024). "We now put these findings in context within the wider frame of autoimmunity against megalin/LRP2 and related antigens such as Fx1A and CD69." (PMID 32701075, 2020). "A previous report described an increased CD62Llo population among NIK KO CD25+ cells, and the presence of these activated Tregs (which also expressed increased CD69, CD45RB, and CD44) was suggested to contribute to autoimmunity." (PMID 24073289, 2013). "We found an increase in CD8+ memory T cells in lymphoid tissue during the earliest phases of autoimmunity, even before clinical onset of RA, accompanied by an increased frequency of non-circulating or recently activated (CD69+) CD8+ T cells in lymphoid tissue and peripheral blood." (PMID 27195110, 2016). "Furthermore, nT1D participants presented considerably lower CD69+ CD4+ activation response compared to HC, indicating the potential effect of the immune exhaustion and tolerance as the result of previous exposure to miRNAs involved in the development of T1D autoimmunity and beta-cell destruction." (PMID 32296701, 2020). "Interestingly, similarly to the case of CD69, LAG3 deficiency does not result in basal lymphocyte dysfunction but rather impairs tolerogenic mechanisms upon antigen activation leading to exacerbated autoimmunity." (PMID 25880134, 2015).
lung carcinoma (17 papers, 2018 to 2025). "Treatment with plasma of lung cancer patients inhibited lymphocytes proliferation and reduced CD69 expression, which caused suppression of lymphocyte activity." (PMID 34633989, 2021). "In a screen for lung cancer prognostic genes, it was found to correlate with the amount of immune cell infiltration such as CD69 and M0 macrophages." (PMID 40337271, 2025). "In lung cancer patients who responded to PD-1/PD-L1 blocking, the expression of CD69 was upregulated, indicating that CD69 expression levels can effectively predict cancer response to PD-1/PD-L1 blockade immunotherapy." (PMID 37880277, 2023). "Clinical research demonstrated that the level of CD44+, CD54+, and CD69+ lymphocytes in peripheral blood of lung cancer patients were significantly lower than the health and rose after chemotherapy." (PMID 34633989, 2021). "It has been reported previously that ENT increases T-cell activation markers such as CD69 in PBMCs derived from lung cancer patients." (PMID 34819039, 2021). "We therefore analyzed data from lung cancer patient samples in The Cancer Genome Atlas (TCGA) database and found that CD69 was significantly decreased in cancer samples compared with normal tissues." (PMID 29453833, 2018). "The present results indicate that ketamine induces lung carcinoma cell apoptosis by activating CD69 gene transcription." (PMID 29453833, 2018). "Stage III cancers had significantly higher expression of CXCL2, CD69, CCR4, and TNFRsf13c, all of which have been implicated as potential therapeutic targets in other malignancies, or in the case of CCR4, poor prognosis in lung cancer." (PMID 35881197, 2023). "Furthermore, immunofluorescence showed the ability of TIM-3-ECD to bind to the surface of lung cancer A549 cells and to provide an additional boost for the expression of the lymphocyte activation marker CD69 in anti-CD3/CD28 activated human PBMC." (PMID 37588136, 2023). "The exposure of lung carcinoma cells to ketamine results in an increased level of CD69 expression." (PMID 29453833, 2018). "In our sample of lung cancer effusions, within the memory T cell population, approximately 15% of the CD8+ cells expressed CD69 and/or CD103." (PMID 40285480, 2025). "CD44, GIMAP4, CD69, and CCL4L2 were among the most relevant contributing markers defining the predictive ML signatures on lung cancer samples." (PMID 40989699, 2025). "CD69 and CD103 are also highly co-expressed on TRM from lung cancers, however we only saw co-expression on 10% of CD4+ TRM and 20% of CD8+ TRM." (PMID 40285480, 2025). "For example, although the numbers vary somewhat, in lung cancer, it has been reported that between 30%–60% of CD8 TILs and 5%–40% of CD4 TILs express CD69 and/or CD103 and were categorized as TRM." (PMID 40285480, 2025). "Analysis of TCGA lung cancer datasets (LUAD and LUSC) showed that while CD69 exhibited positive correlation with PD-1 and PD-L1, SBK1 exhibited negative correlation." (PMID 36045683, 2022). "In addition, we demonstrated that CD8+ T cells in a patient with lung cancer exhibited lower expression of cytotoxic marker PRF1 and activation marker CD69 in co-cultured with A549 for 24 h compared to a healthy volunteer." (PMID 36688994, 2023). "In order to understand the difference of activated lymphocytes in peripheral blood between lung cancer patients and healthy person, we analyzed the percentages of CD69+ lymphocytes by gating CD45+CD3+CD69+ T cells and CD45+CD3-CD69+ non-T cells, respectively." (PMID 37180581, 2023).
glioma (15 papers, 2017 to 2025). A benign or malignant brain and spinal cord tumor that arises from glial cells (astrocytes, oligodendrocytes, ependymal cells). "Elevated circulating Hsp70 levels and a higher prevalence of activated CD3−/CD56+/CD94+/CD69+ NK cells were associated with an improved OS in grade 3 gliomas, whereas high Hsp70 levels and low CD3+/CD4+ frequencies were associated with an adverse OS in GBM." (PMID 38137456, 2023). "In pediatric and young adult gliomas, TRM cells with the CD45RO+CD69+CCR7− phenotype are present in tumor tissues and are linked to better patient prognosis." (PMID 39802636, 2025). "Our data showed the power of BiKE to induce activation of NK cells judged by the expression of CD25 and CD69 markers and mediate the killing of glioma cells in vitro and in vivo." (PMID 37443750, 2023). "Intriguingly, the T-αFGL2 treatment increased CXCR3 expression on CD69+CD8+ TM cells in glioma-bearing brains compared with T-Ctr treatment." (PMID 36759517, 2023). "Fluorescence activated cell sorting (FACS) analysis and immunofluorescence staining highlighted a statistically significant increase in CD8+ TRM cells (CD103+ and CD69+ CD8+ T cells) in gliomas compared to control samples (meningioma)." (PMID 36289717, 2022). "Flow cytometric analysis of co-cultures of peripheral blood-derived NK cells with GBM6 and GBM39 patient-derived xenograft lines revealed significantly increased activation of NK cells (CD25+CD69+) and increased glioma cell killing following BiKE treatment compared to controls (n = 4, p < 0.01)." (PMID 37443750, 2023). "Additionally, an improved OS in grade 3 glioma patients was found to be associated with a higher frequency of CD3−/CD56+/CD94+ NK cells and an upregulated expression of the activatory marker CD69 on NK cells." (PMID 38137456, 2023). "CD69 + and Iba1 + cells were more frequently located inside glioma tissues in GD3S-KO mice, while they were located mainly around glioma tissues in control mice." (PMID 38590763, 2024). "Herein, we performed CD69 immunostaining on human and mouse T cells following in vitro activation and post immune checkpoint inhibitors (ICI) in an orthotopic syngeneic mouse glioma model." (PMID 37426447, 2023). "In this study, TCL+TIO3 induced an increased population of NK cells and higher ratios of CD69+ or NKG2D+ NK cells in splenocytes compared with those of the TCL group, resulting in stronger cytotoxic activities against glioma." (PMID 36776837, 2023). "Significant differences in the lymphocyte frequencies between the Hsp70low and Hsp70high glioma patients were observed for CD3−/CD56+, CD56+/CD94+, and CD56+/CD69+ NK cells." (PMID 38137456, 2023). "The proportion of all NK cell subsets as well as the mean fluorescence intensity values (mfi) of CD94 (69 vs. 43), CD69 (43 vs. 39), and CD56 (70 vs. 40) were higher in a grade IV glioma patient compared to a healthy control, respectively." (PMID 34079819, 2021). "To corroborate our hypothesis that CD69 is an ideal imaging agent for monitoring ICI response by virtue of early T-cell activation, we measured CD69 expression on T cells following activation in vitro and on GL261 glioma cells." (PMID 37426447, 2023). "Because tumor cells, including gliomas, can aberrantly express lineage nonspecific molecules, we evaluated CD69 expression on the GL261 glioma cell line and dissociated GL261 tumor tissue post ICI treatment by flow cytometry." (PMID 37426447, 2023). "Similarly, increased TIM-3 expression and decreased IFNγ expression were demonstrated in tumor-infiltrating CD8+ T cells in a syngeneic glioma mouse model, although potential changes in BAT3, FOXO1, BLIMP1, and CD69 expression were not reported in this study." (PMID 39513882, 2024).
diabetes (14 papers, 2010 to 2025). "CD69 is a marker for early immune cell activation and plays a complex and sometimes paradoxical role in inflammation and diabetes." (PMID 41465460, 2025). "Supporting an important role for CD69+ activated T cells in diabetes, CD69 expression has been found to be increased in T cells from insulin-stimulated whole blood from T1D patients compared to healthy controls as well as in diabetic compared to nondiabetic T cells from NOD mice." (PMID 38487540, 2024). "As autoreactive cytotoxic CD8+ T cells drive pancreatic β-cell destruction in diabetes, it seems plausible that changes in the frequency and activation (CD69+ and IFN-γ+) of CD8+ T cells observed in NOD.Ifih1R/R mice likely contributed to the accelerated diabetes observed in NOD.Ifih1R/R females." (PMID 38487540, 2024). "The significant increase in CD69 mRNA in both control and diabetic healed tissues suggests its role in immune regulation, but its increased protein expression in control healed tissues compared to diabetic control tissues suggests that CD69 expression may be impaired during diabetes." (PMID 41465460, 2025). "Moreover, B and T cell responses are altered in people with diabetes in several ways for instance, reduced expression of co-stimulatory molecules (CD69, CD28, CD40 ligand) or interleukin-12 receptor on T cells which leads to lower production of interferon and granzyme B." (PMID 36105809, 2022). "This study aims to investigate the effects of hyperglycemia on the gene and protein expression of CD36, CD69, CD274, and TLR-7 during wound healing using a rat model of induced diabetes." (PMID 41465460, 2025). "Treatment of BDC mice with αCD3 Ab (clone 2C11), a therapy shown to reverse diabetes in NOD mice, however, decreased expression of Foxo1-axis genes but increased expression of TCR-driven genes (Irf4, Nr4a1, Cd25, Cd69, Tbx21) in PLN BDC CD4+ T cells." (PMID 34314385, 2021). "The percentage of monocytes and neutrophils expressing CD69 and CD142 was significantly higher in known diabetes and prediabetes, but, lowest in screen-detected diabetes (both p ≤ 0.016)." (PMID 28091589, 2017). "Participants with T1D, but not with T2D, showed a significant decrease in the frequency of S‐specific CD4+ T cells, identified as CD154+CD69+, compared with people without diabetes (approximately 2.7‐fold decrease in T1D compared with the no diabetes group)." (PMID 41367201, 2025). "In mouse studies, the proportion of CD4+ and CD8+ T cells in the liver was not affected by diabetes; however, the activated CD4+(CD69+) and CD8+(CD69+) T cell counts were higher in diabetes (FC = 2.5 and 2, respectively, both p < 0.05) vs. non-diabetes." (PMID 40362271, 2025).
hepatocellular carcinoma (14 papers, 2013 to 2025). A malignant tumor that arises from hepatocytes. "Higher CD69 expression by γδ T cells is linked with better survivability in regard to hepatocellular carcinoma." (PMID 40136700, 2025). "Cocultivation of HCV replicon or virus-transfected hepatoma cells with DC cultures led to an upregulation of CD69 expression on both cell types analyzed." (PMID 27385030, 2016). "In hepatocellular cancer, miR-21 was predicted to regulate “immune response” by targeting CD69, STAT3, CCL20 and SMAD7, in which STAT3 and SMAD7 are important signaling molecules for immune response." (PMID 24278370, 2013). "● miR-92b suppressed CD69 on natural killer (NK) cells and predicted the risk of post-transplant HCC (hepatocellular carcinoma) recurrence; ● miR-92b was upregulated and could monitor chemoresistance in small lung cancer; ● miR-92b decreased in early CRC (colorectal cancer) cancer." (PMID 36304546, 2022). "Background/Objectives: Liver and tumor-infiltrating T cells in hepatocellular carcinoma (HCC) are heterogeneous, comprising the CD69+ tissue-resident T-cell and the CD69− circulating T-cell populations." (PMID 40361474, 2025). "In hepatocellular carcinoma (HCC) and pancreatic cancer patients, two distinct FoxP3+/− TI Treg subsets exhibiting differential expression patterns of CTLA-4, PD-1, CD25 and CD69 were identified in tumor-infiltrating lymphocyte (TIL) populations." (PMID 27509527, 2016). "Importantly, CD69+CD49a+ Vγ9Vδ2 TRM isolated from the human liver displayed a greater increase in effector function (IFN-γ, IL-2 expression) compared to their non-resident (CD69−CD49a−) Vγ9Vδ2 T-cell counterparts when co-cultured with ZOL-treated hepatoma cell lines." (PMID 35296658, 2022).